POLR3G (RNA polymerase III subunit G)
Diseases named in the same sentence as POLR3G in open-access papers (continued):
Sharing a sentence is not in itself a finding about the gene and the disease.
cancer (continued). "POLR3GL is ubiquitous, whereas POLR3G is enriched in stem and cancer cells." (PMID 30820548, 2019). "However, both mRNA and protein of POLR3G are elevated in the cancer cells relative to the untransformed cells." (PMID 30820548, 2019). "Thus, understanding and potentially targeting POLR3G expression may present a promising strategy for disrupting Pol III-driven growth in cancer contexts." (PMID 37894362, 2023). "Altogether, POLR3G is most significantly associated with unfavorable outcomes in pan-cancer analyses compared to all other Pol III subunits, residing in the top 3.39% of unfavorable genes, further highlighting the need to understand the regulation and function of POLR3G." (PMID 37894362, 2023). "Notably, patient-matched breast, thyroid, and prostate primary cancer tissues are characterized by less, or insignificantly higher POLR3G bias, suggesting POLR3G dysregulation may be less common in these and potentially other contexts." (PMID 35637192, 2022). "Here, we profiled the relationship between POLR3G (RPC7α) or POLR3GL (RPC7β) expression and outcomes among cancer patients, stratified by cancer subtype." (PMID 37894362, 2023). "Upregulation of POLR3G, which is driven by MYC, identifies a subgroup of patients with unfavorable survival outcomes in specific cancers, further implicating the POLR3G-enhanced transcription repertoire as a potential disease factor." (PMID 35637192, 2022). "Analysis of Pol III isoform biases and downstream chromatin features identifies loss of POLR3G and snaR-A during differentiation, and conversely, re-establishment of POLR3G gene expression and SNAR-A gene features in cancer contexts." (PMID 35637192, 2022). "Taken together, these findings implicate POLR3G in disease progression and identify Pol III subunit RPC7α as a promising molecular target in cancer." (PMID 36710885, 2022). "In cancer, upregulation of POLR3G, but not POLR3GL, is associated with poor survival outcomes among patients, suggesting differences between RPC7α and RPC7β further influence disease progression and may translate into future biomarkers and therapeutic strategies." (PMID 36710885, 2022). "BC200 ncRNA, which also presents evidence of gene-level correlation with POLR3G availability, has been similarly reported to be enhanced by MYC and essential for viability and proliferation in cancer contexts." (PMID 35637192, 2022). "Building on the putative POLR3G-sensitive repertoire in THP-1 and primary immune cells, we sought to profile Pol III identity and downstream activity in cancer contexts." (PMID 35637192, 2022). "Results of this study revealed that POLR3G was highly expressed in multiple cancer types, including TCC, and qRT-PCR further confirmed that POLR3G was elevated in T24 cells compared to SV-HUC-1 cells." (PMID 33194434, 2020). "POLR3G binds to telomerase reverse transcriptase (TERT), a protein that enhances the proliferative capacity of many stem and cancer cell types." (PMID 30820548, 2019). "Our pan-cancer chromatin survey identifies a broad region of significant negative correlation approximately 400 Kb downstream of POLR3G." (PMID 37894362, 2023). "In contrast to the gene-internal regulatory element, accessibility of the POLR3G gene promoter does not correlate with POLR3G expression in cancer." (PMID 37894362, 2023). "Antithetical to ZNF131, MXD4 was identified as the strongest negative TF correlate of POLR3G expression in cancer and, we show, is a negative determinant of POLR3G mRNA abundance." (PMID 37894362, 2023). "POLR3G, one form of RNA polymerase III, was mainly expressed in stem and cancer cells." (PMID 35874741, 2022). "The contrasting relationship between POLR3G and POLR3GL overexpression and cancer outcomes is, on its face, incongruous with a model in which both RPC7 subunits are functionally identical and raises questions about the regulation and function of Pol III identity in disease." (PMID 36710885, 2022).
cancer (continued). "POLR3G is a DNA-directed RNA polymerase III subunit that is enriched in stem and cancer cells." (PMID 34760709, 2021). "Pluripotency factors OCT4 and NANOG, which play critical roles in POLR3G expression during early development, are notably omitted from the list of features that correlate with POLR3G levels in cancer, consistent with the absence of OCT4 and NANOG in most contexts." (PMID 37894362, 2023). "However, the oncogenic transcription factor MYC also localizes to the POLR3G gene promoter in multiple cell lines and cancer contexts, presumably in the absence of OCT4 and NANOG, suggesting Pol III identity may be shaped by a distinct transcription factor repertoire in disease contexts." (PMID 37894362, 2023).
infection (3 papers, 2017 to 2024). The state of being infected such as from the introduction of a foreign agent such as serum, vaccine, antigenic substance or organism. "In early stages of the infection, the bta-miR-247 would downregulate POLR3G, an activator of the RNA polymerase III that functions as a non-self dsDNA sensor and is implicated in the activation of DNA-driven innate immune responses." (PMID 38167436, 2024). "For example, TNFSF13B, FOS, POLR3G and PRKCE were down-regulated at 3 h post infection, while ITGB7 and THBD were up-regulated." (PMID 28938587, 2017). "The POLR3G downregulation might be responsible, at least in part, for the blockade of the innate immune responses that allows MAP persistence within infected macrophages during the long-term subclinical stage of the infection." (PMID 38167436, 2024).
neurodevelopmental disorder (1 paper, 2024). A behavioral and cognitive disorder with onset during the developmental period that involves impaired or aberrant development of intellectual, motor, or social functions. "Although the significance of POLR3G variants in ASD has not been well investigated, several studies have linked neurodevelopmental disorders to variants in genes associated to the transcriptional machinery, including parts of RNA polymerase III29–32." (PMID 38649688, 2024).
POLR3G also shares sentences with these, for which no sentence is quoted: esophageal carcinoma (2 papers); hepatocellular carcinoma (2); bladder urothelial carcinoma (1); colon adenocarcinoma (1); colorectal adenocarcinoma (1); COVID-19 (1); lung squamous cell carcinoma (1); ovarian carcinoma (1); stomach adenocarcinoma (1); thyroid carcinoma (1); uterine corpus endometrial carcinoma (1).